TERT (telomerase reverse transcriptase)
Diseases named in the same sentence as TERT in open-access papers (continued):
Sharing a sentence is not in itself a finding about the gene and the disease.
cancer (continued). "The findings discovered recurrent HBV integration events at the known and potential cancer-related TERT, MLL4, and CCNE1 genes, which demonstrated increased gene expression in HCC compared to normal tissue." (PMID 35518785, 2022). "Nevertheless, the cancer-related genomic and epigenetic aberrations identified in TERT-NHUCs at least partially recapitulate in vivo pathogenesis process of UCs." (PMID 36713366, 2022). "Given all the oncogenic effects of TERT, GABPB1 and GABPA-mediated TERT upregulation is expected to promote cancer progression." (PMID 35326537, 2022). "The detection of cancer-related RNA molecules in plasma, specifically cell-free circulating TERT mRNA, can be potentially used as a disease marker." (PMID 36203446, 2022). "The TERT gene is located on chromosome 5p, and its gain or amplification is widespread in many cancers." (PMID 36394204, 2022). "In humans, TERT is specifically expressed in most immortalized cells, including 85–90% of all human cancers, germ cells, and stem cells." (PMID 35741087, 2022). "Overall, these add to the idea of a tightly regulated, multi-faceted control of TERT transcription, which only becomes unchecked during cancer transformation." (PMID 35053525, 2022). "TERT is an essential component of the telomerase complex that is over-activated in many cancer types as the primary mechanism for maintaining telomere length as these cells replicate." (PMID 36358665, 2022). "It is known that some wild-type cancer cell lines display mono-allelic TERT expression and others bi-allelic expression, but it is unclear what determines mono- or bi-allelic expression in these cases." (PMID 36011010, 2022). "Yet, each cancer can exhibit a variety of TERT expression‐related events with different prevalence pattern across cancer types, which hampers the translation of the molecular knowledge into a prognostic tool for daily clinical practice." (PMID 35979662, 2022). "We also propose that SMG6 and TERT are novel molecular target candidates for LATS2-inactivated cancers such as MM." (PMID 36335095, 2022). "It is evident from the findings earlier that hypermethylation of the TERT UTSS region is required to activate TERT transcription in cancer cells, which is further supported by the detailed analysis of TC cells bearing mutant TERT promoters." (PMID 36394204, 2022). "WT1, minor histocompatibility A (HA)-1, telomerase (TERT), and survivin, neoantigens, and cancer-testis antigens (CTAs) have been reported as TAAs and have been explored in preclinical trials." (PMID 35356211, 2022). "In preoperative molecular FNAC diagnostics, the aggressiveness of cancers with the most frequently occurring mutations (BRAF, RAS, RET/PTC, TERT, PAX8/PPAR-γ, RET proto-oncogene) is correlated with the extent of the planned surgical treatment." (PMID 35884820, 2022). "GABPB1 is reported to activate TERT gene expression and has been proposed as a cancer therapeutic target." (PMID 35326537, 2022). "Among the selected cancer stemness genes, we found that TERT, MYC, CD44, BMI1, ABCB1 and ABCG2 were highly expressed in OCM1 cells compared to their expression in C918 cells, whereas the expression of ZEB1 was opposite to that of the stemness genes." (PMID 35404029, 2022). "Whereas TERT is a telomerase that immortalizes cancer cells by stabilizing telomere length, PD-L1 is an immune checkpoint protein that interacts with PD-1 to induce cancer immune escape." (PMID 35205610, 2022). "Our cancer cell line analysis was different in several ways from many previous TERT promoter methylation and expression studies." (PMID 36011010, 2022). "Numerous studies have shown that TERT, beyond its telomere-lengthening function, concurs with cancer development via multiple activities, also including the regulation of T-cell function particularly in virus-infected cells." (PMID 36358677, 2022).
cancer (continued). "Due to its near universality, high specificity to cancer cells, and ability to confer replicative immortality, telomerase and specifically its catalytic subunit hTERT (human TERT) have become an attractive target for anticancer therapy." (PMID 36437244, 2022). "An earlier study demonstrated cytolytic activity of TERT-specific cytotoxic T lymphocytes (CTLs) against several cancers, including leukemia." (PMID 35356211, 2022). "Cancer cells overcome this restriction and maintain their telomeres by re-expressing TERT, the catalytic protein component of telomerase." (PMID 35267575, 2022). "TERT is often a target of genomic change to stabilize telomeres through the many cycles of replication that cancer cells undergo." (PMID 35229492, 2022). "TERT (Telomerase reverse transcriptase) is a ribonucleoprotein polymerase that, in progenitors and cancer cells, maintains telomere ends for the replication of chromosome termini in most eukaryotes." (PMID 35503718, 2022). "Aggressive cancers maintain telomere integrity usually by expressing TERT mRNA, although by various means." (PMID 36011010, 2022). "Cancer-specific TERT expression and mediated telomerase activation have always generated great enthusiasm for the potential clinical applications of TERT/telomerase-based assays in cancer." (PMID 35327529, 2022). "Peptide vaccines consist of short amino acid chains derived from the full-length TERT sequence that are administered as single agents or in combination with immune modulatory or other anti-cancer agents." (PMID 35159075, 2022). "This pattern of TERT promoter hypermethylation is cancer specific and significantly correlates with increased TERT expression and poorer patient outcome." (PMID 36011010, 2022). "We found that 11.5% (3/26) of driver genes including PMS2, CDKN2A and TERT are significant in the prognosis at least two cancer types." (PMID 35962343, 2022). "Both G > A transitions were described as the most frequent in a large core of various cancers, 73% of which overexpressed TERT." (PMID 35884575, 2022). "The re‐expression of TERT in cancer cells allows the repair of critically short telomeric lengths and maintenance of an unlimited replication rate in cancer cells." (PMID 35979662, 2022). "Relatedly, the presence of mutations, rearrangements, or duplications that hyperactivate telomerase are pathognomonic in numerous cancers, where they upregulate TERT through a variety of genetic and epigenetic mechanisms." (PMID 35159075, 2022). "The endogenous TERT peptides produced by cancer cells can be recognized by major histocompatibility complex (MHC) class I or class II molecules and trigger an adaptive immune response." (PMID 35903534, 2022). "For example, it has been reported that the CRISPR-mediated correction of the TERT promoter prolongs the survival of mice with experimental cancers." (PMID 36552277, 2022). "This latter domain included a region that was later referred to as the TERT hypermethylated oncological region (THOR), which can play a role as a potential diagnostic and prognostic marker in different cancer types." (PMID 35327497, 2022). "TAPAS depletion and over-expression in cancer cells led to significantly enhanced and diminished TERT expression, respectively." (PMID 36713366, 2022). "The increased telomerase activity observed in most cancers has led to the development of several strategies to target TERT." (PMID 36291091, 2022). "TERT expression is typically suppressed in somatic cells, in contrast, 90 percent of cancer cells maintain stable expression of this enzyme." (PMID 36624801, 2022). "High TERT expression and its mitochondrial localization contribute to metabolic aberrations in (non‐thyroid) normal and cancer cells." (PMID 36394204, 2022).
cancer (continued). "In vitro, TERT protein is highly immunogenic to peripheral blood T lymphocytes in healthy people and cancer patients, indicating that TERT-reactive T-cell precursors are present in the blood and are not missing in the thymus." (PMID 35903534, 2022). "During differentiation, telomerase reverse transcriptase (TERT) levels and telomerase activity are decreased as compared to stem or cancer cells that are actively dividing." (PMID 35769259, 2022). "The activation of telomerase in cancer cells is a complicated process involving at least three steps: TERT expression, telomerase assembly and telomere elongation." (PMID 35669414, 2022). "TERT and MYC, for example, have been linked to enhanced drug sensitivity of cancer cells to nelarabine, palbociclib, hydroxyurea, cytarabine, fluphenazine, fludarabine, carmustine, and other drugs." (PMID 34853590, 2021). "In cancers, DNA hypermethylation with the TERT promoter is a prevalent telomerase-activating mechanism that can act independently of or in conjunction with promoter mutations." (PMID 33413203, 2021). "Our data showed that GABPA knockdown substantially reduced the recruitment of p-ERK to mutant TERT promoter in cancer cells carrying both BRAFV600E and TERT promoter mutations." (PMID 33483600, 2021). "Dogan and Forsyth report methylation and mutation of the Tert promoter in 53% and 31%, respectively, of TERT expressing cancer cell lines." (PMID 34681626, 2021). "Recently, small‐molecule inhibitors for TERT or telomerase RNA have been developed and showed a response in several cancers." (PMID 34477310, 2021). "To this end, we assessed T-cell responses directed specifically against TERT, known for its frequent expression in various cancer types and its high immunogenicity." (PMID 34144673, 2021). "TERT expression is commonly silenced in somatic cells; however, it is observed during the embryonic period and in some stem cells, especially in cancer cells." (PMID 34477310, 2021). "For example, in our work, the pan-cancer TS269 promoter was obtained by fusion of strong cancer promoters of the TERT and BIRC5 genes." (PMID 33804861, 2021). "Here, we found that TAF-I maintains the telomere integrity through the epigenetic regulation of the TERT gene transcription in human cancer cells." (PMID 34489496, 2021). "To guide future studies, we clustered cancer cell lines with tumors from related origin based on TERT isoform expression patterns." (PMID 33924498, 2021). "Telomerase reverse transcriptase (TERT) not only maintains telomere, but also potentiates cancer stemness and metastasis via modulating the activity of related factors, such as NF-κB and Wnt/β-catenin." (PMID 33435156, 2021). "TERT fusions have previously been suggested to represent a rare mechanism of TERT activation in cancer." (PMID 34033669, 2021). "In the majority of cancers, tumors attain replicative immortality primarily through telomerase activation via increased TERT transcription, providing telomerase as the preferred target for drug development in cancer therapeutics." (PMID 34947936, 2021). "On the other hand, overexpression of TERT and TERC are associated with cancer progression as they enhance cell proliferation." (PMID 33599797, 2021). "Abnormalities in TERT expression or promoter mutations in HCC have been sporadically studied and reported to be associated with cancer recurrence and progression." (PMID 33946181, 2021). "Two specific non-coding mutations in the TERT promoter required for the activation of TERT transcription by GABP occur with high frequency in aggressive cancer types." (PMID 33541355, 2021).
cancer (continued). "Understanding the mechanisms of aberrant TERT expression is a fundamental question for human cancer, and TERT is also a potential clinical target for improving cancer diagnosis and prognosis." (PMID 34858826, 2021). "In this result, these commonly related genes including TERT, KRAS, and CDKN2A were also highly associated with cancer progression." (PMID 34442467, 2021). "The potential clinical application of TERT expression and telomerase activation or telomerase activity inhibition remains at the forefront of a number of cancer therapeutic strategies." (PMID 33802026, 2021). "In approximately 90% of cancers immortality is achieved by reactivation of telomerase, involving reactivation of the TERT gene expression." (PMID 33547950, 2021). "It has been shown that β-catenin can interact directly with the mouse and human cancer cells or cancer stem cells TERT promoter." (PMID 33869033, 2021). "The main mechanism of telomere maintenance (85–90% of cancers) is reactivation of Telomerase, the enzyme that extends telomeres and particularly of its reverse transcriptase subunit (TERT)." (PMID 34944589, 2021). "Because a variety of cancer cells acquire the reactivation of telomerase, the transcriptional activation of TERT is a crucial step for occurrence and recurrence of human cancer cells." (PMID 34489496, 2021). "Results from our study provide novel evidence of the shared inherited basis of human cancers and expand our understanding of the role played by the TERT-CLPTM1L region in cancer development." (PMID 34355204, 2021). "As trafficking of TERT into nucleus is disrupted in TCAB1 knockdown cancer cells, it suggests that the oncogenic potential of TCAB1 acts through enhancing telomerase activity in the nucleus." (PMID 33599797, 2021). "In contrast, many studies reported that DNA hypermethylation of the TERT promoter is positively related to telomerase activity in cancers." (PMID 33413203, 2021). "Telomerase reverse transcriptase (TERT) is the main factor responsible for these aspects in the great majority of cancers, including HCC, where it is present in >95% of HCC cases." (PMID 34069740, 2021). "If non-coding driver mutations in regulatory regions are present, we similarly expect they would affect cancer genes more often than other genes, as exemplified by the presence of non-coding driver hotspots in the TERT promoter." (PMID 33986299, 2021). "Since TERT reactivation has played a pivotal role in maintaining the telomeres and thereby supporting infinite cell division in cancer cells, many researchers have sought to determine the genetic basis for TERT reactivation in different types of cancer." (PMID 33483600, 2021). "DNA methylation, histone methylation–acetylation, and non-coding RNAs all play roles in the regulation of TERT expression in various biological processes including ageing and cancer." (PMID 33802026, 2021). "Telomerase reverse transcriptase (TERT) plays an important role in telomere lengthening and oncogenesis in many human cancers." (PMID 33547950, 2021). "Telomerase reverse transcriptase (TERT) activation is involved in cancer development through diverse activities other than mediating telomere elongation." (PMID 34947936, 2021). "Mechanistically, as a crucial signaling molecule in Wnt pathway, β-catenin improves the expression of telomerase reverse transcriptase (TERT), a ribonucleoprotein that prevents the loss of telomeres in cancer stem cells." (PMID 34789315, 2021). "Multiple miRNAs target the 3′-UTRs and ORFs of TERT, regulating its activity in several cancer cells." (PMID 33802026, 2021). "Of relevance to future tissue-specific studies, we clustered cancer cell lines with tumors from related origin based on TERT isoform expression patterns." (PMID 33924498, 2021).
cancer (continued). "In the majority of human primary cancers (~90%), TERT expression/telomerase activity is perceptible." (PMID 33869033, 2021). "TERT is immunogenic, TERT-based immunogens easily overcome tolerance making TERT a perfect immunogen for cancer vaccines making TERT an attractive target for cancer immunotherapy." (PMID 34067686, 2021). "It has also been studied in cancer cell lines with tumors of relevant origin based on TERT isoform expression patterns." (PMID 34681758, 2021). "The revelation that cancer cells express TERT epitopes as a surface marker enabled the development of immunotherapies to target telomerase." (PMID 34440361, 2021). "Together, these data highlight the role played by TERT in the regulation of the miR500 cluster and the relevance of such crosstalk in cancer progression." (PMID 33713376, 2021). "These somatic mutations in TERT promoter create de novo consensus binding sites (CCGGAA) for the E-twenty-six (ETS) transcription factor family, providing a mechanism for cancer-specific activation of hTERT expression." (PMID 33776938, 2021). "Several groups have studied the reactivation of the mutant TERT promoter using recent genome editing tools and identified cancer-type-specific co-regulators that drive TERT expression in cells harboring the mutant TERT promoter." (PMID 33599797, 2021). "For the remaining 11 cancer types, we postulated potential subtype-specific mechanisms by which TERT expression and TL are altered, and their resultant functions." (PMID 33924498, 2021). "Several cancer types (14/29) presented at least one significant (p < 0.05) difference related to TERT expression or TL ratio." (PMID 33924498, 2021). "PCA biplots across cancer types, with some exceptions, showed that FL-TERT, TERT_238.6, and TERT_656.1 had strong positive correlations with each other." (PMID 33924498, 2021). "In this study, we found that TAF-I is a novel regulator of telomere DNA synthesis through the transcriptional activation of TERT through epigenetic mechanism in human cancer cells." (PMID 34489496, 2021). "It is well known that several nucleotide mutations in the TERT promoter such as C228T and C250T, both generating new binding sites for ETS family transcription factors, are frequently observed in human cancer cell lines." (PMID 34489496, 2021). "Reactivation of the multi-subunit ribonucleoprotein telomerase is the primary telomere maintenance mechanism in cancer, but it is rate-limited by the enzymatic component, telomerase reverse transcriptase (TERT)." (PMID 33924498, 2021). "TERT polymorphisms, such as rs2736100-CC genotype features, were reported more frequently than the wild-type TERT promoter in patients with cancer." (PMID 34947936, 2021). "TERT has also been linked to altered redox status and, specifically, to higher levels of reduced glutathione (GSH) and reduced oxidative stress in cancer cells." (PMID 33397920, 2021). "We used Uniform Manifold Approximation and Projection (UMAP) to project average TERT isoform expression patterns in primary tumors with Cancer Cell Line Encyclopedia (CCLE) for 19 cell origin types." (PMID 33924498, 2021). "Given that in most somatic cells, telomerase activity is limited by TERT expression, cancer cells thus require reactivation of TERT expression to restore telomerase activity." (PMID 33599797, 2021). "Although cancer cell lines are immortalized, often through TERT activation, cell lines can serve as models for living tissues in aspects such as gene expression and have been deeply profiled." (PMID 34486523, 2021). "Sp1 acts as a repressor of TERT in cancer cells by forming a complex with Sp3, while in Kaposi sarcoma associated herpes virus (KSHV), Sp1 becomes an activator via interactions with latency-associated antigen—briefly known as LANA." (PMID 34440361, 2021).